VIP (vasoactive intestinal peptide)
Diseases named in the same sentence as VIP in open-access papers (continued):
Sharing a sentence is not in itself a finding about the gene and the disease.
Hypokalemia (22 papers, 2013 to 2025). An abnormally decreased potassium concentration in the blood. "The Verner-Morrison syndrome, also called the WDHA syndrome, arises from an overproduction of VIP by a tumor such as a neuroblastoma causing watery diarrhea, hypokalemia, and achlorhydria as symptoms." (PMID 40520658, 2025). "Paraneoplastic diarrhea (VIPoma syndrome) is caused by vasoactive intestinal peptide (VIP) secretion from pancreatic neuroendocrine tumors (VIPomas) or medullary thyroid carcinoma, resulting in secretory diarrhea, hypokalemia, and dehydration." (PMID 40867266, 2025). "The profound watery secretory diarrhea caused by excessive VIP secretion leads to massive losses of potassium, bicarbonate, sodium, and fluids, resulting in hypokalemia, metabolic acidosis, and severe dehydration." (PMID 40647278, 2025). "Another uncommon functional pancreatic neuroendocrine tumor is VIPoma, which is composed of D1 cells, secretes vasoactive intestinal peptide (VIP), and causes large volume diarrhea, hypokalemia, and achlorhydria." (PMID 36507125, 2022). "Watery diarrhea, hypokalemia, metabolic acidosis due of enteric bicarbonate loss and hypo- or rarely achlorhydria are clinical features of VIP-secreting tumors and generally begin several years before diagnosis." (PMID 33815297, 2021). "Usually, patients present with abdominal pain, diarrhea, vomiting, bloody stools, constipation, and obstruction, which in some cases is accompanied by iron-deficiency anemia, elevated serum vasoactive intestinal peptide and hypokalemia, and growth and motor development retardation." (PMID 35783634, 2022). "High levels of circulating VIP were responsible of the rapidly evolving clinical picture with massive dehydration and weight loss along with severe hyperchloremic metabolic acidosis and hypokalemia due to the profuse untreatable diarrhea." (PMID 33815297, 2021). "This case illustrates that chronic diarrhea with metabolic dysregulation (e.g. hypokalemia) can be the first and only symptom in patients with VIP-secreting neuroblastoma which can result in delayed diagnosis of neuroblastoma." (PMID 40520658, 2025). "In conclusion, chronic diarrhea with metabolic dysregulation (e.g. hypokalemia) can be the first and only symptom in patients with a VIP-secreting neuroblastoma." (PMID 40520658, 2025). "Excessive VIP secretion can result in treatment-resistant diarrhea with electrolyte disturbances (e.g., hypokalemia, hypochlorhydria, hypercalcemia, and hypomagnesemia can develop) and dehydration." (PMID 40520658, 2025). "Before resection, all patients with VIPoma require correction of dehydration, hypokalemia, and other metabolic abnormalities, and preoperative administration of octreotide can reduce circulating VIP levels." (PMID 40941664, 2025). "Patients with VIPomas classically present with watery diarrhea, hypokalemia, and achlorhydria and have elevated plasma levels of VIP." (PMID 40291307, 2025). "Biochemical testing revealed severe hypokalemia and elevated plasma levels of vasoactive intestinal polypeptide (VIP), leading to the diagnosis of a VIP-secreting pheochromocytoma." (PMID 39355460, 2024). "Watery diarrhea, hypokalemia and achlorhydria (WDHA) is a rare syndrome related to excessive secretion of vasoactive intestinal peptide (VIP)." (PMID 33815297, 2021). "Our patient represents a new case of WDHA syndrome caused by a malignant VIP-secreting PHEO with massive dehydration, severe hyperchloremic metabolic acidosis and hypokalemia due to the profuse diarrhea." (PMID 33815297, 2021). "VIPoma syndrome, also termed pancreatic cholera or Verner-Morrison syndrome, is due to a neuroendocrine tumor that secretes VIP, leading to watery diarrhea, hypokalemia, hypochlorhydria and metabolic acidosis." (PMID 33398457, 2021). "A rare syndrome of watery diarrhea associated with hypokalemia and achlorhydria (WDHA) due to hypersecretion of VIP was described initially by Verner and Morrison in 1958." (PMID 25081061, 2014).
Hypokalemia (continued). "A rare syndrome of watery diarrhea, hypokalemia and achlorhydria (WDHA) is usually caused by pancreatic endocrine tumors that secrete excessive vasoactive intestinal polypeptide (VIP)." (PMID 25081061, 2014). "Immunoreactive VIP was found predominantly in neuronal components of the composite tumors with watery diarrhea-hypokalemia-achlorhydria syndrome." (PMID 23587063, 2013). "In rare cases, patients with neuroblastoma may present with paraneoplastic syndromes, such as watery diarrhea, hypokalemia, and achlorhydria (WDHA syndrome), linked to the secretion of vasoactive intestinal peptide (VIP)." (PMID 40520658, 2025). "They oversecrete vasoactive intestinal peptide (VIP), which causes severe diarrhea and hypokalemia." (PMID 37568572, 2023). "Similarly, somatostatin can be measured to aid in the diagnosis of somatostatinoma and VIP can be measured in the plasma to diagnose a VIPoma in conjunction with hypokalemia and achlorhydria." (PMID 36291833, 2022). "Secretion of vasoactive intestinal polypeptide (VIP), as typically observed in patients with non-β islet cell tumors of the pancreas, may cause watery diarrhea, hypokalemia, and hypochlorhydria." (PMID 29177551, 2018). "VIPoma, also termed pancreatic cholera, Verner-Morrison syndrome or WDHH (watery diarrhea, hypokalemia, hypochlorhydria) syndrome due to VIP-expressing tumor tissue in the liver with unknown primary but most likely originating from neuroendocrine differentiation in posttreatment prostate cancer." (PMID 33398457, 2021). "The characteristic watery diarrhea, hypokalemia, and achlorhydria syndrome (WDHA), also referred to as pancreatic cholera, arises from augmented VIP excretion by tumor cells." (PMID 39351119, 2024). "VIP-secreting tumors or VIPomas, are rare in MEN1 and present with watery diarrhea, hypokalemia, and achlorhydria (WDHA)." (PMID 31263451, 2019).
insulinomas (22 papers, 2005 to 2025). "Syndromes associated with hormone-secreting PNET can be manifested in insulinoma, glucagonoma, vasoactive intestinal peptide (VIP)-oma, and gastrinoma." (PMID 22518318, 2012). "Differential diagnoses in patients with chronic diarrhea include vasoactive intestinal peptide-secreting tumors (VIPomas), insulinoma, glucagonoma, somatostatinoma, and carcinoid syndrome." (PMID 40291307, 2025). "In functional tumors, measurement of specific hormones is appropriate [glucagon in glucagonoma, vasoactive intestinal peptide (VIP) in VIPoma, gastrin in gastrinoma, insulin in insulinoma, etc.]." (PMID 36950054, 2023). "Insulinoma, gastrinoma, glucagonoma, vasoactive intestinal peptide (VIP)-oma, and somatostatinoma are some of the endocrine tumors recognized today." (PMID 36498893, 2022). "Of the functional tumors, 6 (26%) were gastrinomas, 9 (39%) were insulinomas, 3 (13%) were glucagonomas, and 4 (17%) were vasoactive intestinal peptide tumors." (PMID 33146734, 2020). "Thirty-eight cases (80.9%) were non-functional PanNETs, and 9 cases (19.1%) were functional PanNETs (6 insulinomas, 1 vasoactive intestinal peptide (VIP) tumor, 1 glucagonoma, and 1 gastrinoma)." (PMID 30975157, 2019). "Functioning pNETs are characterized by specific hormonal hyper secretion and can be classified in insulinomas (45%), gastrinomas (20%), glucagonomas (13%), vasoactive intestinal peptide (VIP)-omas (10%), and somatostatinomas (5%)." (PMID 30223590, 2018). "Common types are insulinoma and gastrinoma, and rare types are VIPoma (vasoactive intestinal peptide), glucagonoma or somatostatinoma." (PMID 26438383, 2015). "Among the tumors, all 3 insulinomas clustered together, separate from the VIP-oma, the glucagonoma and the PP-omas (pancreatic polypeptide producing tumors)." (PMID 15691381, 2005). "For example, insulinomas, glucagonomas, gastrinomas, somatostatinomas, and vipomas are named after the hormones they produce (insulin, glucagon, gastrin, somatostatin, and vasoactive intestinal peptide (VIP), respectively)." (PMID 39201255, 2024). "Insulinoma, gastrinoma, and rare pNET subtypes such as glucagonoma, VIP (vasoactive intestinal peptide)-oma, and somatostatinoma are some examples of functional pNETs, which manifest hormone-related clinical symptoms that may help in diagnosing these tumors at an earlier stage." (PMID 34680266, 2021). "Vasoactive intestinal peptide (VIP)/pituitary adenylate cyclase activating polypeptide (PACAP), and their receptors PAC1, VPAC1 and PAC2 have emerged as important factors in islet cell function (insulin secretion) and growth and differentiation of neuroendocrine tumors including insulinomas." (PMID 28496188, 2017). "PNETs may secrete hormones such as gastrin, insulin, glucagon, vasoactive intestinal polypeptide (VIP) and are referred to as gastrinomas, insulinomas, glucagonomas or VIPomas, respectively, or may be non-secreting (i.e. non-functioning)." (PMID 28504695, 2017).
Headache (20 papers, 2012 to 2026). Cephalgia, or pain sensed in various parts of the head, not confined to the area of distribution of any nerve. "Even though no favorable results were obtained, more promising results have been reported regarding ALD1910, a monoclonal antibody 4000-fold more selective for PACAP38 and PACAP27 than VIP, in an umbellulone-induced rat model of headache." (PMID 38397400, 2024). "Partly consistent with these prior studies, our obtained results also showed elevated serum VIP level in EM patients between headache attacks compared to the control group, but this elevation not observed in the CM patients." (PMID 35002925, 2021). "Headache incidence over the entire 12-hour observational period was greater after VIP (19 [90%]) compared with placebo (7 [33%]; P = .02)." (PMID 34357396, 2021). "The area under the curve (AUC) of headache intensity scores (0-12 hours), as well as the AUC of the superficial temporal artery diameter (0-180 minute) were significantly greater after VIP compared with placebo (AUC0-12h, P = .003; AUC0-180min, P < .001)." (PMID 34357396, 2021). "For example, pituitary adenylate cyclase-activating peptide (PACAP) and vasoactive intestinal peptide (VIP) have been described as being involved in headache pathophysiology." (PMID 29471874, 2018). "Molecular data show that the trigeminal nucleus caudalis is a central structure in headache pathology, comprising various neuropeptides and neurochemicals, including vasoactive intestinal peptide, glutamate, substance P and serotonin, and connecting the pathophysiology of these headache disorders." (PMID 40995873, 2026). "Although PACAP-38 and the closely related peptide VIP (vasoactive intestinal peptide) are well-known as vasoactive molecules, the dilation of cranial blood vessels per se is no longer felt to underlie migraine headaches." (PMID 29536279, 2018). "If AH is a result of vasodilation in the cerebral arteries, elevated levels of CGRP and VIP might be seen in AH and triptans that have shown some benefits for AH may act on these headache biomarkers." (PMID 28815436, 2017). "Immunohistochemical techniques have been used to compare the expression of signal substances with a putative role in headache pathophysiology (CGRP, substance P, neuropeptide Y, VIP) in tumour tissue in patients with and without pituitary adenoma-associated headache." (PMID 22466226, 2012). "Second, the experience of headache likely involves the release of sensory neuropeptides, including calcitonin gene-related peptide (CGRP), vasoactive intestinal peptide (VIP) and also pituitary adenylate cyclase-activating peptide (PACAP)." (PMID 29536279, 2018). "In migraineurs, VIP does not provoke migraine headache, which suggests VPAC1- and VPAC2-receptors to be of minor importance in comparison to the PAC1-receptor." (PMID 30983973, 2019). "Intravenous infusions of PACAP-38, but not VIP, reliably and repeatedly induce delayed migraine-like headaches." (PMID 29536279, 2018). "It is hypothesized that although vasoactive intestinal peptide (VIP) shares the receptors VPAC1 and VPAC2 with PACAP, it is unable to induce robust degranulation, which might explain why it does not cause headache whereas PACAP activity at VPAC1 and VPAC2 does cause headache." (PMID 38481473, 2024).
gastrinoma (19 papers, 2012 to 2025). "Thirty-one percent of patients had functional tumours (carcinoid, gastrinoma, somatostinoma and vasoactive intestinal peptide secreting tumour [VIP]oma)." (PMID 26138480, 2015). "The relatively rare thymic NEN shows the highest risk (hazard ratio [HR] of 4.64), followed by functional glucagon, somatostatin, and vasoactive intestinal peptide (VIP) secreting PNEN (HR 4.29), non-functional PNEN (HR 3.43) and gastrinomas (HR 1.89)." (PMID 39826015, 2025).
Parkinson disease (19 papers, 2012 to 2025). A progressive degenerative disorder of the central nervous system characterized by loss of dopamine producing neurons in the substantia nigra and the presence of Lewy bodies in the substantia nigra and locus coeruleus. "Abnormal VIP-PC circuitry may cause abnormal brain states such as depression, Parkinson’s disease, and epilepsy." (PMID 37237617, 2023). "VIP participates in the pathophysiology of several neurological disorders associated with cognitive disfunction, like depression, autism spectrum disorders, Alzheimer’s disease (AD), Parkinson’s disease (PD) and epilepsy." (PMID 32595454, 2020). "For instance, VIP decreases Aβ accumulation and atrophy in the hippocampus and cortex in mice models of Alzheimer’s disease, and it increases the spine density and prevents dopaminergic cell loss in rat models of Parkinson’s disease." (PMID 33353157, 2020). "PACAP has also been shown to have anti-inflammatory effects in the CNS, while VIP inhibits inflammation in a wide range of neurodegenerative disorders, including Alzheimer’s, Parkinson’s (PD), and Huntington’s diseases." (PMID 38087375, 2023). "An increase in PACP and VIP expression was observed in an animal model of Alzheimer’s and Parkinson’s disease." (PMID 38069321, 2023). "It has been confirmed that VIP interneurons play an important role in the pathology and treatment of neurological disorders, such as Alzheimer’s disease, Parkinsonism and ASD." (PMID 37237617, 2023). "Quantitative results of sudomotor axon reflexes in Parkinson’s disease can be correlated with the presence of VIP in skin samples, to yield a measure of sweat gland activity and neuromodulator expression in the innervating sympathetic sudomotor neurons." (PMID 32930881, 2020). "In this review, we summarize the pieces of evidence showing that PACAP and VIP administration help to preserve cognitive function in different preclinical models of Alzheimer’s disease (AD), Parkinson’s disease (PD) and Huntington’s disease (HD)." (PMID 32765225, 2020). "Further studies have demonstrated that VIP plays a neuroprotective effects in various neurodegenerative diseases developed in animal models including Alzheimer's disease, Parkinson's disease or encephalomyelitis." (PMID 23162538, 2012). "Interestingly, VIP and SST are implicated in the pathogenesis of neurodegenerative diseases, including Alzheimer's disease and Parkinson's disease (PD) through reducing the production of inflammatory mediators such as TNF-α and IL-1β." (PMID 32410857, 2020). "All of this indicates that the VIP/receptors axis could be a novel therapeutic target in multiple sclerosis and Parkinson’s disease." (PMID 31861827, 2019). "The same authors suggest that VIP-mediated neuroprotective effects might also be used for therapy of Parkinson’s disease (PD)." (PMID 31827422, 2019). "Studies addressing the neuroprotective efficacy of VIP in a Parkinson's disease model revealed that VIP could prevent MPTP-induced nigrostriatal dopaminergic neuronal death by blocking microglial activation." (PMID 22328918, 2012). "Finally, the role of the VIP/VPAC axis has also been investigated in Parkinson’s disease." (PMID 31861827, 2019). "Moreover, VIP inhibits the production of pro-inflammatory cytokines as TNFα and/or IL-1β secreted by activated microglia which is involved in neuroinflammation observed in Parkinson's disease or brain trauma models." (PMID 23162538, 2012).
rheumatoid arthritis (19 papers, 2005 to 2024). A chronic, systemic autoimmune disorder characterized by inflammation in the synovial membranes and articular surfaces. "As expected, the cluster associated with high serum levels of VIP was able to confirm the diagnosis of all pathologies with the exception of rheumatoid arthritis (Pearson χ2 = 6.7218, Pr = 0.081)." (PMID 35955723, 2022). "We concluded that the identification of polymorphisms associated with VIP serum levels would complement the clinical assessment of the disease severity in rheumatoid arthritis patients." (PMID 29391448, 2018). "VIP gene polymorphisms, associated with its serum levels, predict treatment requirements in early rheumatoid arthritis." (PMID 30155495, 2018). "In vivo and in vitro studies with different mice autoimmune models, human samples from healthy donors and rheumatoid arthritis patients have demonstrated that VIP is able to decrease pathogenic Th1 and Th17 subsets, and favor Th2, Treg and non-pathogenic Th17 subsets." (PMID 35216459, 2022). "Interestingly, the miRNA signatures that distinguish patients by their serum VIP levels could identify different IMIDs, except rheumatoid arthritis, confirming the diagnostic value of VIP concentration." (PMID 35955723, 2022). "VIP is able to modulate all the stages comprised between the arrival of pathogens and Th cell differentiation in rheumatoid arthritis (RA) through its known anti-inflammatory and immunomodulatory actions." (PMID 31089161, 2019). "Another neuropeptide: vasoactive intestinal peptide (VIP) is also known to reduce the inflammatory and autoimmune components of rheumatoid arthritis in the experimental model." (PMID 28057002, 2017). "The potent immunomodulatory functions of VIP have been demonstrated both in vivo, in a murine model of collagen-induced arthritis, and ex vivo, in cultured fibroblast-like synoviocytes and in peripheral blood lymphocytes of patients with rheumatoid arthritis." (PMID 26881970, 2016). "Additionally, VIP can negatively regulate the Toll-like receptor 4-signaling in rheumatoid arthritis synovial fibroblasts." (PMID 20953422, 2011). "Serum VIP levels and mRNA of VPAC and miRNA expression in peripheral blood mononuclear cells were analyzed from 52 patients with psoriasis, rheumatoid arthritis, Graves’ disease, or spondyloarthritis and from 38 healthy subjects." (PMID 35955723, 2022). "The vasoactive intestinal peptide (VIP) receptors VPAC1 and VPAC2 mediate anti-inflammatory and immunoregulatory responses in rheumatoid arthritis (RA)." (PMID 26881970, 2016). "Furthermore, Delgado and coworkers have described an association between Rheumatoid Arthritis (RA) and some SNPs in the 3′UTR region of VPAC1 that paralleled with a decreased expression of VPAC1 during VIP-mediated signaling in PBMC of patients with RA." (PMID 25390694, 2014). "It shows the therapeutic function in rheumatoid arthritis (RA); however, the protective function of VIP in the progression of OA is not fully explained." (PMID 27553659, 2016).